DNAJC3 (DnaJ heat shock protein family (Hsp40) member C3)
Diseases named in the same sentence as DNAJC3 in open-access papers (continued):
Sharing a sentence is not in itself a finding about the gene and the disease.
scrapie (1 paper, 2008). A fatal disease of the nervous system in sheep and goats, characterized by pruritus, debility, and locomotor incoordination. "The expression of three genes encoding MAPRE3, LOC729073 and DNAJC3 were significantly altered in ileal PP of the scrapie-infected animals as confirmed by real-time PCR." (PMID 18373840, 2008). "Expression of the three genes, MAPRE3, LOC729073 and DNAJC3, were all found significantly altered in ileal PP of scrapie-infected animals." (PMID 18373840, 2008). "The expression of three genes (MAPRE3, LOC729073 and DNAJC3), were found to be significantly altered in scrapie infected lambs (P < 0.05)." (PMID 18373840, 2008).
Sepsis (1 paper, 2023). Sepsis is defined as life-threatening organ dysfunction caused by a dysregulated host response to infection. "Research has shown that stress-induced loss of dynamic balance in ER function was closely related to the progression of sepsis, and DNAJC3 could defend cells against ER stress in response to unfolded proteins." (PMID 37671148, 2023).
steatosis (1 paper, 2014). Increased lipid within the cytoplasm of cells. "We observed a significant overexpression of DNAJC3, EDEM1 (q value <0.01) and BIP (q value = 0.055) in patients with severe steatosis, and of DNAJC3 (q value = 0.023) and EDEM1 (q value = 0.014) in obese patients, compared with patients with no documented steatosis." (PMID 24973751, 2014).
Stroke (1 paper, 2023). Sudden impairment of blood flow to a part of the brain due to occlusion or rupture of an artery to the brain. "Our research findings highlight the significance of genes associated with the UPR pathway, including ATF6, EXOSC5, EEF2, LSM4, NOLC1, BANF1, and DNAJC3, in the occurrence of stroke." (PMID 37891634, 2023).
tauopathy (1 paper, 2024). Neurodegenerative disorders involving deposition of abnormal tau protein isoforms (tau proteins) in neurons and glial cells in the brain. "These genes include Xbp1, Hspa5, Dnajc3, and members of the Pdi family, which overlap with C. elegans homologs in our transcriptomic dataset and are required for xbp-1s-mediated suppression of tauopathy." (PMID 39060347, 2024).
infection (15 papers, 2009 to 2024). The state of being infected such as from the introduction of a foreign agent such as serum, vaccine, antigenic substance or organism. "For instance, Dnajb9L2, Dnajb11, Dnajb12b, Dnajc3, Dnajc20, Dnajc21, and Dnajc29 were up-regulated at only one time point (1.5× fold change cutoff); similarly, Dnajb13 was only down regulated at 24h after infection." (PMID 25542027, 2014). "However, in the liver, and Dnaja4 and Dnajc3 were down-regulated more than five-fold in the liver after infection with ESC." (PMID 25542027, 2014).
tumor (6 papers, 2007 to 2025). "The results of GSEA indicated significant enrichment of multiple tumor–related and immune-related signaling pathways in the DNAJC3 high-expression group." (PMID 41391769, 2025). "DNAJC3, an important member of the heat shock protein family, exhibits bidirectional regulatory effects and plays a role in tumor cell proliferation, apoptosis, autophagy, and drug resistance." (PMID 41315466, 2025). "The results revealed that the DNAJC3 high-expression group was primarily enriched in multiple tumor–related and immune-related pathways." (PMID 41391769, 2025). "In addition, the expression of immune checkpoint molecules is significantly upregulated in patients with high DNAJC3 expression, which once again indicates that DNAJC3 expression is beneficial for the formation of an immunosuppressive tumor microenvironment." (PMID 41391769, 2025). "Therefore, we speculate that DNAJC3 may mediate the resistance of tumor cells to MEK inhibitors by activating the MAPK–ERK signaling pathway." (PMID 41391769, 2025). "Our analyses showed that the transcriptome associated with RASSF1, a tumor suppressor involved in cell cycle regulation and not previously linked to UPR, is highly correlated with the transcriptome of several UPR‐related genes, such as BiP/GRP78, DNAJB9, GRP94, ATF4, DNAJC3, and CHOP/DDIT3." (PMID 36723232, 2023).
cancer (3 papers, 2019 to 2025). A tumor composed of atypical neoplastic, often pleomorphic cells that invade other tissues. "In the HSP40 family, DNAJC25 and DNAJC8 were positively associated with stemness in 16 and 14 cancers, respectively, while DNAJC11 and DNAJC3 were negatively associated with stemness in 25 and 25 cancers, respectively." (PMID 33225964, 2020). "Cancer development was observed by the modulation of genes involved in cell death (HIST1H1T, CASP14, and DNAJC3), cancer related genes (WNT8A and CASC8), gene expression (transcription) (ZNF570 and ZFP42), and metabolism of proteins (CALB2 and KLHDC3)." (PMID 31797963, 2019). "Notably, genes such as TTC3, TMSB4X, MGST1, DNAJC3, and P4HB are closely linked to cancer cell proliferation and migration and may serve as key regulators of CC progression." (PMID 41315466, 2025).
metabolic disorders (3 papers, 2023 to 2025). "As an ERS-related protein, previous studies on DNAJC3 have mainly focused on its protective role in maintaining protein homeostasis by regulating eukaryotic Initiation Factor 2 alpha dephosphorylation in metabolic diseases." (PMID 41391769, 2025).
neurological diseases (2 papers, 2021 to 2022). "While fibroblasts are not the primary site of clinical manifestation, these cell models have been previously shown to be suitable to study the etiology of rare neurological diseases and show very similar levels of DNAJC3 expression to peripheral nerve." (PMID 34692675, 2021).
DNAJC3 also shares sentences with these, for which no sentence is quoted: Hypoinsulinemia (6 papers); colitis (3); glucosuria (3); Cerebral atrophy (2); diabetic retinopathy (2); glaucoma (2); neurodegenerative disease (2); ocular hypertension (2); retinal ischemia (2); type 2 diabetes (2); achromatopsia (1); Alzheimer disease (1); autoimmune disease (1); cholestasis (1); degenerative joint disease (1); Dystonia (1); Hepatic fibrosis (1); influenza (1); insulin-dependent diabetes (1); Intellectual disability (1); lung carcinoma (1); melanoma (1); neuroblastoma (1); oral squamous cell carcinoma (1); peripheral neuropathy (1); phospholipidosis (1); proliferative diabetic retinopathy (1); retinal degeneration (1); retinal disease (1); sensorineural hearing loss (1).
A further 3 diseases each share a sentence with DNAJC3 in 1 paper.